CASP1 (caspase 1)
Description:
Thiol protease involved in a variety of inflammatory processes by proteolytically cleaving other proteins, such as the precursors of the inflammatory cytokines interleukin-1 beta (IL1B) and interleukin 18 (IL18) as well as the pyroptosis inducer Gasdermin-D (GSDMD), into active mature peptides. Plays a key role in cell immunity as an inflammatory response initiator: once activated through formation of an inflammasome complex, it initiates a pro-inflammatory response through the cleavage of the two inflammatory cytokines IL1B and IL18, releasing the mature cytokines which are involved in a variety of inflammatory processes. Cleaves a tetrapeptide after an Asp residue at position P1. Also initiates pyroptosis, a programmed lytic cell death pathway, through cleavage of GSDMD. In contrast to cleavage of interleukin IL1B, recognition and cleavage of GSDMD is not strictly dependent on the consensus cleavage site but depends on an exosite interface on CASP1 that recognizes and binds the Gasdermin-D, C-terminal (GSDMD-CT) part. Cleaves and activates CASP7 in response to bacterial infection, promoting plasma membrane repair. Upon inflammasome activation, during DNA virus infection but not RNA virus challenge, controls antiviral immunity through the cleavage of CGAS, rendering it inactive. In apoptotic cells, cleaves SPHK2 which is released from cells and remains enzymatically active extracellularly. [Isoform Delta]: Apoptosis inactive. [Isoform Epsilon]: Apoptosis inactive.
Synonyms: ICE; IL1BC; P45
Tractability: Small molecule: a drug acting on it is in phase 2 or 3 trials; a structure with a bound ligand is known; a high-quality ligand is known; it has a binding pocket of medium quality; it belongs to a druggable protein family. Antibody: UniProt places it where antibodies can reach, with high confidence; its Gene Ontology location is reachable by antibodies, with medium confidence. PROTAC: UniProt records ubiquitination sites on it; ubiquitination databases record sites on it; its protein half-life has been measured; a small molecule that binds it is known.
Target class: Cysteine protease; Protease; Cysteine protease CD clan; Enzyme; Cysteine protease C14 family
Chemical probes: Ac-YVAD-CHO, ML132, PD080907, PD081081, PD081251, PD081269, PD081293, PD081299, PD081335, PD081452, PD081498, PD081707, PD081739, PD081799, PD081811, PD081875, PD081891, PD082001, PD082183, PD082203, and 34 more
Gene: Protein-coding gene on chromosome 11 (105,023,581 to 105,035,250, reverse strand). Ensembl gene ENSG00000137752.
Subcellular location: Cytoplasm; Cell membrane
Subcellular location (Human Protein Atlas): Cytosol; Nucleoplasm
Pathways (Reactome):
Immune System: Interleukin-1 processing; Interleukin-37 signaling; NOD1/2 Signaling Pathway; Regulation of GBP-mediated host defense; The AIM2 inflammasome; The IPAF inflammasome; The NLRP3 inflammasome
Disease: Purinergic signaling in leishmaniasis infection; SARS-CoV-1 activates/modulates innate immune responses
Programmed Cell Death: Pyroptosis
Gene Ontology:
Molecular function: CARD domain binding; cysteine-type endopeptidase activity; cytokine binding; endopeptidase activity; identical protein binding; kinase binding; protein binding; cysteine-type endopeptidase activator activity involved in apoptotic process; cysteine-type peptidase activity; enzyme binding
Biological process: AIM2 inflammasome complex assembly; cellular response to lipopolysaccharide; cellular response to mechanical stimulus; cellular response to type II interferon; cytokine precursor processing; positive regulation of canonical NF-kappaB signal transduction; positive regulation of inflammatory response; positive regulation of interleukin-1 beta production; positive regulation of interleukin-18 production; positive regulation of NLRP3 inflammasome complex assembly; positive regulation of tumor necrosis factor-mediated signaling pathway; protein autoprocessing; protein maturation; proteolysis; pyroptotic inflammatory response; regulation of inflammatory response; signaling receptor ligand precursor processing; apoptotic process; defense response to bacterium; defense response to virus; icosanoid biosynthetic process; osmosensory signaling pathway; pattern recognition receptor signaling pathway; positive regulation of apoptotic process; protein processing; and 4 more
Cellular component: AIM2 inflammasome complex; canonical inflammasome complex; cytoplasm; cytosol; NLRP1 inflammasome complex; NLRP3 inflammasome complex; plasma membrane; protease inhibitor complex; protein-containing complex; IPAF inflammasome complex; microtubule; nucleolus
Genetic constraint (gnomAD): Loss-of-function variants: 13 observed, 25.32 expected, observed/expected ratio (o/e) 0.51, 90% interval 0.33 to 0.82. The upper end of that interval is the gene's LOEUF score, 0.82, which puts it in group 3 of 6, group 1 being the genes least tolerant of losing a copy. Missense variants: 334 observed, 358.43 expected, observed/expected ratio (o/e) 0.93, 90% interval 0.85 to 1.02. Synonymous variants: 111 observed, 122.93 expected, observed/expected ratio (o/e) 0.9, 90% interval 0.77 to 1.06.
Homologues: Orthologues: chimpanzee CASP1 (98% identical), pig CASP1 (72% identical), mouse Casp1 (62% identical), rat Casp1 (61% identical), Caenorhabditis elegans ced-3 (23% identical), tropical clawed frog casp8 (22% identical), zebrafish casp8 (21% identical), Drosophila melanogaster Dronc (18% identical), Caenorhabditis elegans csp-1 (18% identical), Drosophila melanogaster Decay (18% identical), zebrafish casp20 (18% identical), Caenorhabditis elegans csp-2 (17% identical), and 3 more. Paralogues in human: CASP4 (48% identical), CASP5 (46% identical), CASP12 (38% identical), CASP9 (23% identical), CASP2 (22% identical), CARD16 (22% identical), CASP8 (22% identical), CASP3 (21% identical), CASP10 (19% identical), CASP7 (19% identical), CASP6 (17% identical), CFLAR (17% identical), and 4 more.
Diseases named in the same sentence as CASP1 in open-access papers:
CASP1 is named in the same sentence as 620 diseases in open-access papers, as found by Europe PMC text mining. Sharing a sentence is not in itself a finding about the gene and the disease. The quoted sentences say what the papers report.
Sepsis (197 papers, 2009 to 2026). Sepsis is defined as life-threatening organ dysfunction caused by a dysregulated host response to infection. "Recent studies have shown the key role of NLRP3/caspase-1/GSDMD-dependent pyroptosis signaling pathway in the regulation of sepsis-associated organ dysfunction." (PMID 40708650, 2025). "In another report, the mechanism of FXR negatively regulating the NLRP3 inflammasome was through FXR interacting with NLRP3, as well as caspase 1 in protein levels during sepsis associated with cholestasis." (PMID 38172440, 2024). "The NLRP3/caspase-1 pathway-induced pyroptosis has also been linked to cognitive impairment following sepsis." (PMID 38665289, 2024). "Pyroptosis, a proinflammatory cell death caused by caspase-1 during infection, is increasingly seen as a key mechanism of sepsis, mediated by NLRP3 inflammasome activation." (PMID 38705396, 2024). "In the present study, our findings demonstrated previously unappreciated associations of circulating EV caspase-1/miR-126 levels with sepsis outcomes." (PMID 37180111, 2023). "We further examined caspase-1 activity in circulating EC-derived EVs and analyzed its association with sepsis outcomes including mortality, ARDS and ARF." (PMID 37180111, 2023). "Caspase-1 activity in EVs was detected and their association with sepsis outcomes including mortality, ARDS and ARF was analyzed." (PMID 37180111, 2023). "The NLRP3 inflammasome complex, consisting of NLRP3, apoptosis-associated speck-like protein containing CARD (ASC) and caspase-1, plays a fundamental role in dysfunctional endothelium during sepsis." (PMID 37587410, 2023). "In this study, we examined the potential causes and pathogenesis of increased sepsis susceptibility in inflammatory skin diseases using a mouse dermatitis model: keratin 14-driven caspase-1 is overexpressed (KCASP1Tg) in mice on a high-fat diet." (PMID 38203647, 2023). "Enhanced caspase-1 activity and declining miR-126 levels in circulating EVs are associated with sepsis-related organ failure and mortality." (PMID 37180111, 2023). "Erbin protects against sepsis-associated encephalopathy by attenuating microglial pyroptosis via the IRE1α/Xbp1s-Ca2+ axis, and NLRP3/Caspase-1 pathway-induced pyroptosis mediates cognitive deficits in a mouse model of sepsis-associated encephalopathy." (PMID 38037161, 2023). "Pyroptosis is inflammation-associated caspase-1-dependent programmed cell death, which confers a crucial role in sepsis." (PMID 35508474, 2022). "Our previous studies have shown that the overactivation of caspase-1 is closely associated with the development and prognosis of sepsis." (PMID 34992715, 2021). "LC3B-deficient mice produced more caspase-1-dependent cytokines in sepsis models and were susceptible to LPS-induced mortality than controls." (PMID 34777380, 2021). "In this study, we found that the expression of NLRP3-associated proteins, including NLRP3, ASC, caspase-1, and IL-1β, was significantly upregulated at 12 and 24 h after sepsis." (PMID 32454788, 2020). "Renal and pulmonary expression of NLRP3 and Caspase 1 were unchanged in response to sepsis, although tissue levels of inflammasome-associated cytokines IL-1β and IL-18 did increase in after CLP." (PMID 32555710, 2020). "We further show the underlying mechanism of these effects; namely, the sepsis-induced formation of NLRP3 inflammasome leads to caspase-1 activation and triggers inflammatory cascades and pyroptosis." (PMID 30276509, 2019). "Murine caspase-12 deficiency confers resistance to sepsis and its presence exerts a direct suppressive effect on caspase-1, resulting in enhanced vulnerability to bacterial infection and septic shock." (PMID 29719506, 2018). "Pyroptosis is a caspase-1 dependent cell death, associated with proinflammatory cytokine production, and is considered to play a crucial role in sepsis." (PMID 24454930, 2014).
Sepsis (continued). "Similarly, puerarin protected against sepsis-associated encephalopathy by inhibiting NLRP3/Caspase-1/GSDMD pyroptosis pathway and reducing blood-brain barrier damage." (PMID 40708650, 2025). "Caspase-1 and miR-126 in EVs have been implicated in lung injury and sepsis." (PMID 37180111, 2023). "In addition to caspase-1, miR-126 has been implicated in vascular injury during sepsis and is one of the most abundant miRNAs in the EC-derived EVs." (PMID 37180111, 2023). "Therefore, caspase-1 inhibitors can protect against brain injury caused by sepsis to some extent, mainly by blocking the microglial pyroptosis pathway and reducing the release of pro-inflammatory cytokines." (PMID 35572571, 2022). "In addition, interdiction of pyroptosis through caspase-1/-11 or gasdermin D gene deficiency induces mice resistant to endotoxin-induced sepsis." (PMID 33002070, 2020). "In this context, caspase-1 has been associated with both inflammation and apoptosis in sepsis." (PMID 24643116, 2014). "Also, caspase-1 deficient mice are sheltered from disease of excessive inflammation, such as bacterial-induced sepsis, and are markedly resistant to the lethal effects of endotoxin." (PMID 25400921, 2014). "Pyroptosis is a caspase-1 dependent cell death, associated with proinflammatory cytokine production, and is considered to play a crucial role in the dysregulation of inflammatory/immune responses in sepsis." (PMID 24454930, 2014). "In this study, NLRC4 was highly expressed in all patients with sepsis; therefore, it is reasonable to believe that NLRC4 may cause pyroptosis by activating caspase-1 and promoting the inflammatory response, which consequently leads to the development of sepsis." (PMID 36765335, 2023). "Our data demonstrated that EV caspase-1 activity and miR-126 levels are associated with the development of organ failures and mortality and may serve as novel biomarkers and/or therapeutic targets for sepsis." (PMID 37180111, 2023). "Recent evidence suggests that circulating extracellular vesicles (EVs) and their content caspase-1 and miR-126 may play a critical role in modulating vascular injury in sepsis; however, the association between circulating EVs and sepsis outcomes remains largely unknown." (PMID 37180111, 2023). "In addition, it was reported that biglycan-deficient mice show improved survival in LPS-induced sepsis and less severe inflammation in both models of sterile inflammatory renal injury and LPS-induced sepsis because of decreased levels of active caspase-1 and mature IL-1." (PMID 31739592, 2019). "Inhibition of NLRP3/ASC/Caspase-1 mediated pyroptosis-related signaling pathway, thus improving sepsis-related ALI." (PMID 40918090, 2025). "By regulating the key molecule GSDMD, pyroptosis activates the NLRP3 inflammasome and caspase-1-dependent apoptosis, contributing to myocardial dysfunction in sepsis." (PMID 40526611, 2025). "The intracellular caspase-1 levels were higher in the sepsis cohort than the control cohort as shown in our earlier studies." (PMID 40051620, 2025). "Caspase-1 promotes pyroptosis and amplifies inflammatory responses, contributing to the pathogenesis of sepsis." (PMID 40555741, 2025). "For instance, phillyrin prevented sepsis-induced acute lung injury through inhibiting the NLRP3/caspase-1/GSDMD-dependent pyroptosis signaling pathway." (PMID 40708650, 2025). "A 2-fold significant increase in secreted caspase-1 in C19wSepsis cohort was observed compared to C19NoSepsis cohort (*p=0.0311), and the Sepsis Alone cohort had a 2-fold significant increase compared to C19NoSepsis cohort (*p=0.019)." (PMID 40051620, 2025). "In summary, ECG exerts an ameliorative effect on sepsis-induced ALI by inhibiting the NLRP3/Caspase-1/GSDMD signaling pathway." (PMID 41496909, 2025). "It is possible that caspase-1 is secreted into microvesicles and caspase-1 was shown to regulate lymphocyte apoptosis in sepsis." (PMID 40051620, 2025).
Sepsis (continued). "It comprises NLRP3, which detects danger and recruits molecules; caspase-1, essential for cytokine maturation and processing gasdermin D for cytokine release and sepsis; and ASC, bridging NLRP3 and caspase-1." (PMID 38922058, 2024). "By reducing the expression of the PERK/ATF4/CHOP signaling pathway, the NLRP3 inflammasome’s hyperactivation and caspase-1-dependent pyroptosis are inhibited, which improving sepsis outcomes." (PMID 38434710, 2024). "Inhibits sepsis mediated by NLRP3-Caspase-1-GSDMD and has neuroprotective properties in various neurological disorders such as HD, AD, epilepsy, cognitive disorders, anxiety disorders, and depression." (PMID 38370420, 2024). "Maintaining the stability of the ER seems crucial in preventing excessive activation of the NLRP3 inflammasome, decreasing caspase-1-mediated pyroptosis, and enhancing sepsis results." (PMID 38434710, 2024). "Since the uncontrolled activation of NLRs (mainly NLPR3) and GSDMD have been described both in human and mouse models of sepsis, caspase 1/4/5/11 have been proposed as drug targets." (PMID 38256033, 2024). "The present study identifies a novel regulatory relationship between amyloid-β (Aβ) and the inflammasome-caspase-1 axis as key innate immune mediators that define sepsis outcomes." (PMID 38410714, 2024). "Together, these data suggest that Aβ is indicative of a sepsis-specific, infection-associated ICU patient endotype, and caspase-1 is indicative of a pro-inflammatory ICU patient endotype." (PMID 38410714, 2024). "In our advanced mechanistic study involving the CLP sepsis model, we found that F4/80-positive macrophages exhibited increased caspase-1 activity in lung tissues of CLP mice, while circMAPK1 silencing attenuated these effects." (PMID 39300342, 2024). "Inhibiting pyroptosis by inhibiting NLRP3 and caspase-1 expression has shown protective effects on cognitive impairment following sepsis in newborn rats." (PMID 38665289, 2024). "In an induced sepsis animal model, a study was conducted to inhibit the expression of GSDMD and its lysed form GsdMd-NT by administering the caspase-1 inhibitor VX765 as a neuroprotective therapy to reduce pyrodeath of brain cells during sepsis." (PMID 39027435, 2024). "IMD1 − 53 provide protection against heart injury and inflammation by attenuating the NLRP3/Caspase-1/IL-1β pathway during sepsis." (PMID 38616256, 2024). "Studies have also suggested that the administration of inhibitors of NLRP3/caspase-1 pathway-mediated pyroptosis (e.g., MC950, melatonin) is protective against sepsis-associated encephalopathy, spinal cord injury, and motor neuron damage in rats." (PMID 38256033, 2024). "The presence of a putative cleavage site along with the strong clinical correlation between Aβx-40 and caspase-1 levels in sepsis patients suggested a regulatory relationship between the two." (PMID 38410714, 2024). "Aβx-40 and caspase-1 are potentially useful early indicators of sepsis and its attendant organ injury." (PMID 38410714, 2024). "The transcription factor USF2 activates TSP-1 to activate the TGF-β/NLRP3/Caspase-1 signaling pathway, resulting in promotion of the oxidative stress response and stimulation of pyroptosis in sepsis-induced AKI." (PMID 38516004, 2024). "YTH N6-Methyladenosine RNA Binding Protein 1 (YTHDF1), m6A reader protein, induced NLRP3 ubiquitination and inhibited caspase-1-dependent pyroptosis to alleviate sepsis." (PMID 38022612, 2023). "Nonetheless, studies employing infections with different pathogens suggest that the role of caspase 1 or caspase 11 in the pathogenesis of sepsis is pathogen-, tissue-, and/or organ-specific." (PMID 37998332, 2023). "A growing body of evidence has confirmed that inhibiting caspase-1 is beneficial in sepsis, as it can reduce inflammation, apoptosis and pyroptosis, and attenuate organ injury." (PMID 37180111, 2023).